ZBTB10 (zinc finger and BTB domain containing 10)
Diseases named in the same sentence as ZBTB10 in open-access papers (continued):
Sharing a sentence is not in itself a finding about the gene and the disease.
cancer (13 papers, 2012 to 2025). A tumor composed of atypical neoplastic, often pleomorphic cells that invade other tissues. "It has been reported that ZBTB10 is involved in pyruvate kinase metabolism, which is a key process of the glycolysis response essential for cancer progression." (PMID 37834257, 2023). "It was found in previous studies that ZBTB48 and ZBTB10 were involved in the progression of different cancers." (PMID 36098743, 2022). "Immunohistochemistry and RNA expression analysis indicated that IDI1, BNIP3, IFRD1, and ZBTB10 were significantly differentially expressed in cancer and healthy tissues." (PMID 34226298, 2021). "Our results showed that miR-27a suppressed ZBTB10 in cancer cells and antisense miR-27a induced ZBTB10 expression with downregulation of Sp1, Sp3, Sp4 and pro-oncogenic Sp-regulated genes." (PMID 34072678, 2021). "miR-27a has been reported to be a oncogenic miRNA in various cancer cells, and its expression and target gene (ZBTB10) levels were dependent on the dose of genistein." (PMID 22928040, 2012). "ZBTB10 is a transcriptional “Sp repressor” regulated by miR-27a in cancer cell lines, and previous studies show that drug-induced Sp repression is due to ROS-dependent disruption of miR-27a:ZBTB10." (PMID 23194063, 2012). "Although CPXM1, CCL4, ZBTB10 and B3GNT2 have not been reported to be related to the prognosis of ALL, the four genes we screened are all closely related to cancer, and we have reason to believe that they may also be potential genes for predicting the prognosis of ALL." (PMID 36407095, 2022).
infection (2 papers, 2015 to 2024). The state of being infected such as from the introduction of a foreign agent such as serum, vaccine, antigenic substance or organism. "It is intriguing that infection with the mSLS4 virus causes an increase in overall SUMO conjugate levels, and this is reflected in either reduced loss of presumed sumoylated forms of certain proteins during mSLS4 infection, or indeed an increase in their abundance (as in the case of ZBTB10)." (PMID 26200910, 2015). "Key markers such as ZBTB10, DUSP8, and HIST1H2BG, predominantly expressed in VRI_stage2, suggest specialized roles during infection beyond the transitional differentiation observed in uninfected conditions." (PMID 39735182, 2024).
adenocarcinoma (1 paper, 2022). A common cancer characterized by the presence of malignant glandular cells. "Next, we examined protein levels of ZBTB10 in a panel of prostate cell lines and found that AR-negative PC3 and NE-like LASCPC01 cells expressed lower ZBTB10 than AR-positive VCaP, LNCaP, C4-2, and 22Rv1 adenocarcinoma cells." (PMID 35306527, 2022).
ZBTB10 also shares sentences with these, for which no sentence is quoted: glioblastoma multiforme (1 paper); head and neck tumors (1); prostate carcinoma (1); sensitive (1); uterine fibroids (1).